GLS2 (glutaminase 2)
Diseases named in the same sentence as GLS2 in open-access papers (continued):
Sharing a sentence is not in itself a finding about the gene and the disease.
tumor (continued). "GLS2 expression has been reported to downregulate the phosphatidylinositol 3-kinase/protein kinase B (PI3K/AKT) signalling pathway in HCC and GBM cell lines, which has been related to a tumour suppressor function for GLS2." (PMID 39796278, 2025). "Key questions to be solved include deeper mechanistic insights and how generalizable these GLS2-induced changes are in other tumour types and in organs expressing GLS2 in physiological conditions, as it happens in the liver." (PMID 39796278, 2025). "The function of GLS2 as either a tumour suppressor or an oncogene is contingent upon the specific type of tumour in question." (PMID 40598593, 2025). "GLS1 promotes tumor cell growth in various cancers, while GLS2 suppresses cancer cell proliferation and migration." (PMID 40370433, 2025). "This reduction in GLS2 correlated with enhanced tumour cell proliferation and migration, alongside decreased apoptosis." (PMID 41154605, 2025). "GLS2 (liver-type) typically exerts its tumor - suppressing function by promoting ferroptosis, and its regulatory role in glutaminolysis is essential for tumor growth inhibition." (PMID 41293169, 2025). "Overexpression of GLS2 suppressed these malignant behaviours, implying a tumour-suppressive function for GLS2 in GC." (PMID 41154605, 2025). "Special focus is given on the glutaminase isoform, GLS1 (kidney type glutaminase), as the other isoform GLS2 (Liver type glutaminase) acts as a tumour suppressor in some conditions." (PMID 38939098, 2024). "The interaction between Myc and GLS2 is subject to ongoing debate, varying with cell type and tumour characteristics." (PMID 39273225, 2024). "Since GLS2 is a tumor suppressor, relatively few therapeutic studies related to GLS2 have been reported in the literature." (PMID 38172980, 2024). "In contrast, GLS1 and GLS2 appear to serve opposing roles in tumour development, attributed to various regulatory mechanisms and their distinct immunological, kinetic, and molecular properties." (PMID 39273225, 2024). "Numerous studies have reported a higher expression of GLS1 and lower expression of GLS2 in various tumor types, including liver cancer and colorectal cancer." (PMID 38218942, 2024). "In certain cancers, GLS2 is overexpressed and contributes to malignancy; however, in other cancers, it serves as a tumor suppressor." (PMID 39050886, 2024). "GLS correlates with tumor growth and proliferation, while GLS2 can function as a context-dependent tumor suppressor." (PMID 38929183, 2024). "In other words, GLS1 has been established as an oncogene, but GLS2 functions as a tumor suppressor gene." (PMID 38172980, 2024). "GLS2 is an enzyme responsible for the metabolism of Gln, which serves as a primary source of energy and a fundamental building block in tumor cells." (PMID 39050886, 2024).
tumor (continued). "In GBM, GLS is commonly overexpressed and GLS2 is usually silenced, appearing to show some tumor-suppressive properties." (PMID 36672480, 2023). "GLS2 exhibits a tumor-suppressive function by inhibiting Rac1 activity, which in turn inhibits the migration, invasion and metastasis of malignancy cells." (PMID 37754250, 2023). "Astonishingly, the pro-tumorigenic effect, assessed as tumor volume and the number of lung metastases, was more pronounced when GLS2 overexpression was accompanied by GLS knockdown." (PMID 38067269, 2023). "GLS2 is considered to be a tumor suppressor while GLS1 has the potential to facilitate tumor development." (PMID 37249801, 2023). "Collectively, the overwhelming majority of data collected to date clearly indicate that, in HCC, GLS2 is a bona fide tumor suppressor." (PMID 38067269, 2023). "For example, overexpression of GLS2 greatly reduces tumor cell proliferation and cell colony formation, and GLS2 was confirmed as a tumor suppressor in HCC that inhibits tumor function by regulating glutamine metabolism." (PMID 38078880, 2023). "While in some cancer types GLS2 is overexpressed and drives cancer development, in some other types it is downregulated and behaves as a tumor suppressor gene." (PMID 38067269, 2023). "In some cancers, GLS2 expression is regulated by oncoproteins and clearly contributes to tumorigenesis by supporting cancer cell proliferation and tumor growth." (PMID 38067269, 2023). "In some types of cancer, this enzyme is overexpressed and fuels malignancy; however, there are some types of cancer in which GLS2 plays a role opposite to that of a tumor suppressor." (PMID 38067269, 2023). "Similar results were obtained in the intracranial tumor model, indicating, for the first time, that GLS2 exerts anti-glioma effects in in vivo settings." (PMID 38067269, 2023). "Glutaminase GLS2 is an enzyme that metabolizes glutamine, one of the main sources of energy and building blocks in tumor cells." (PMID 38067269, 2023). "GLS2 encodes LGA and GAB isoforms, whose role in the tumor appears to be more complicated and context-dependent." (PMID 36672480, 2023). "Some studies have reported that GLS2 overexpression reduces tumor growth, suggesting that GLS2 acts as a tumor suppressor." (PMID 38017510, 2023). "Unexpectedly, adjacent liver tissue had more GLS1 expression than tumours, whereas the liver type glutaminase GLS2 was slightly increased in tumours compared with adjacent tissues." (PMID 35538890, 2022). "It has been reported that GLS2 upregulation increases tumor metastasis and correlates with poor survival." (PMID 36135194, 2022). "Growing evidence shows that GLS1 and GLS2 are related to tumor progression and growth rate, and tumor proliferation can be delayed by gene manipulation or inhibition/activation of these enzymes." (PMID 35310969, 2022). "Physcion 8-O-beta-glucopyranoside (PG) exerted an anti-tumor role in GC by downregulating inhibitory effect of miR-103a-3p on glutaminase 2 (GLS2) expression, and the upregulating ROS level, intracellular Fe(2+) level, and malondialdehyde (MDA) generation." (PMID 34381023, 2021).
tumor (continued). "Glutaminase isoenzymes GLS and GLS2 play apparently opposing roles in cancer: GLS acts as an oncoprotein, while GLS2 (GAB isoform) has context specific tumour suppressive activity." (PMID 33610185, 2021). "Protein expression analyses of the tumor relevant genes CREM GLS2, PER3 and TXNIP mostly showed a diametrical regulation compared to mRNA expression in both cell lines under acidotic conditions." (PMID 33407762, 2021). "With respect to invasive tumours, increased expression of GLS2 protein predicted longer recurrence-free intervals." (PMID 34439127, 2021). "Both low and high proliferative luminal tumours showed weak positive correlation between GLS2 protein and ALDH18A1 (p < 0.001), ALDH4A1 (p < 0.01), ATF4 (p = 0.001), PRODH (p < 0.001), SLC38A2 (p ≤ 0.001) and SLC7A11 (p < 0.001)." (PMID 34439127, 2021). "In the tumor samples, F2, GLS2, IDO2, and PLAUR were shown to be significantly upregulated, while GNG7, PIK3CG, and ST3GAL6 were significantly down-regulated." (PMID 33619235, 2021). "The upregulation of GLS2 in cancer cells induced an antiproliferative response with cell cycle arrested at the G2/M phase and reduced tumor cell colony formation in HCC." (PMID 33194749, 2020). "We made use of three distinct experimental approaches for elucidating the nuclear localization of GLS2 proteins in human tumor cells." (PMID 32042057, 2020). "Positive associations with several glutamine metabolic enzymes were also detected, among these, GLS2 and glutamate dehydrogenase (GLUD1) which are associated with tumours of good prognosis and favourable patient outcome." (PMID 32200487, 2020). "It was suggested the molecular mechanism of GLS2 inhibition-mediated tumor suppression was activity-independent stabilization of the EMT-related microRNA, miR-34a both in vitro and in vivo." (PMID 31027222, 2019). "Conversely, the expression of GLS2, the mitochondrial isoform of glutaminase, inversely correlates with tumor stage, tumor size, and prognosis in HCC." (PMID 31027222, 2019). "GLS and GLS2 have distinct patterns of expression and regulation in different organs and tumor types." (PMID 31652551, 2019). "Although GLS2 has been suggested to act as a tumor suppressor gene, nothing is known about its role in S. aureus infection." (PMID 30289878, 2018). "In order to deeply investigate the impact of DUOX1, GLS2, FBP1 and age on DFS and OAS, we developed a simple score composed of the four variables to predict the risk of HCC relapse and death after tumor resection." (PMID 27079415, 2016). "Then a multivariate analysis with Cox’s proportional hazard model manifested that DUOX1, GLS2, FBP1 and age were independent risk factors for the prognosis of HCC patients after tumor resection." (PMID 27079415, 2016).
tumor (continued). "Recent studies have shown that, in contrast to the tumorigenic effect of GLS1, GLS2 displays a tumor suppressive function." (PMID 26751560, 2016). "We found that tumor capsule invaded was the only parameter showing clinical significance associated with differential expression of GLS1 and GLS2." (PMID 25844758, 2015). "In aggregate, these results reveal a novel mechanism deciphering context-dependent regulation of metabolic heterogeneities, uncovering a previously unsuspected link between Myc, GLS2 and tumor metabolism." (PMID 26528759, 2015). "In particular, abrogation of GLS2 expression recovered radiosensitivities of resistant tumor cells, in vitro and vivo, concomitant with a significant increase in ROS production." (PMID 26528759, 2015). "In line with this, we found that HCC patients who exhibited high GLS1 expression suffered decreased survival, and that patients who exhibited high GLS2 expression in tumor tissues survived longer." (PMID 25844758, 2015). "GLS2 was mainly expressed in non-tumor hepatocytes, and there was a metabolic switch from GLS2 to GLS1 in HCC." (PMID 25844758, 2015). "We found that GLS1 was highly expressed in HCC; whereas, expression of GLS2 was mainly confined to non-tumor hepatocytes." (PMID 25844758, 2015). "GLS1 expression is elevated in many primary tumors and tumor cell lines, while GLS2 expression appears to be relatively limited in cancer." (PMID 26439804, 2015). "A recent article demonstrate that GLS2 plays an important role in tumor suppression in HCC, and that negative regulation of PI3K/AKT signaling contributes greatly to this function of GLS2." (PMID 25844758, 2015). "The exact mechanisms involved in regulation of the tumor-promoting versus tumor-suppressing functions of GLS2 are currently unclear." (PMID 26528759, 2015). "Of note, when results of GLS1 and GLS2 staining in tumor tissues were combined, the sensitivity of these markers for HCC pathological diagnosis reached 100%." (PMID 25844758, 2015). "In contrast to GLS1, GLS2 is widely accepted as tumor suppressor and inhibits tumor formation via ectopic expression." (PMID 26402672, 2015). "Taken together, results from this study demonstrated an important role of GLS2 in tumor suppression in HCC through its negative regulation of the PI3K/AKT signaling." (PMID 24797434, 2014). "Compared with the non-tumor liver tissues (3 tissues from Origene), all of these cell lines showed clearly decreased mRNA levels of GLS2." (PMID 24797434, 2014). "Compared with non-tumor liver tissues (3 tissues from Origene), GLS2 mRNA levels were clearly decreased in different HCC cell lines, including Huh1, Huh7, PLC/PRF/5, and Hep3B cells." (PMID 24797434, 2014). "Taken together, our results demonstrate that GLS2 plays an important role in tumor suppression in HCC, and the negative regulation of PI3K/AKT signaling contributes greatly to this function of GLS2." (PMID 24797434, 2014). "In contrast, in the matched 21 adjacent non-tumor liver tissues, 20 samples showed positive staining for GLS2 (+) and 1 showed weak staining for GLS2 (±) (p<0.0001; HCCs vs. adjacent non-tumor liver tissues)." (PMID 24797434, 2014). "More importantly, we found that Gls2 expression was significantly downregulated in 85% of human liver tumor tissues when compared to the adjacent non-tumor tissues and distant normal tissues." (PMID 24330717, 2013).
tumor (continued). "It has been reported that Gls2 can exert its tumor suppressive function via reduction of oxidative stress-induced DNA damage and mutations." (PMID 24330717, 2013). "Whether these activities for GLS2 take place in other tumour types, or are even related to the role of GLS2 in normal physiological conditions, remains a key open question to be solved." (PMID 39796278, 2025). "Therefore, the precise mechanism of action of GLS2 remains to be elucidated, and there is heterogeneity between different tumours." (PMID 40598593, 2025). "GLS is considered prooncogenic and overexpressed in many tumours, while GLS2 may act as prooncogenic or as a tumour suppressor." (PMID 39796278, 2025). "Whether this inhibition of PDH activity by GLS2 is a generalizable characteristic of GLS2 in other tumour types or even in physiological conditions is another key question to be addressed." (PMID 39796278, 2025). "Additionally, the isozymes glutaminase 1 (GLS1) and GLS2 have opposing roles in tumors: GLS1 exhibits oncogenic properties, whereas GLS2 functions as a tumor suppressor." (PMID 40723225, 2025). "However, GLS2 exhibits tumor heterogeneity and is found to be upregulated in specific malignancies, such as breast cancer, thereby promoting oncogenesis." (PMID 40028341, 2025). "In contrast to GLS1, the expression of GLS2 is predominantly confined to non-tumor hepatic cells." (PMID 40028341, 2025). "GLS2 is also involved in the metabolism of Gln, which is a crucial energy source for tumor cells." (PMID 39050886, 2024). "GLS1 has oncogenic properties, while GLS2 has been described as a tumor suppressor." (PMID 38218942, 2024). "GLS1 and GLS2 are isozymes that play opposite roles in tumor development." (PMID 38218942, 2024). "In addition, a study revealed that Gls2 KO mice have a marked propensity to develop late HCC, which suggests that GLS2 plays a role in ferroptosis and consequent tumour suppression." (PMID 38993573, 2024). "Compared to GLS1, GLS2 is more diverse in promoting or inhibiting tumour metastasis." (PMID 37829798, 2023). "Moreover, GLS1 and GLS2 are considered as independent prognostic factors for HCC, with GLS2 negatively correlated to tumor stage and overall survival, possibly for its anti-proliferative effects as a result of blocking G2/M phases of the cell cycle." (PMID 37108625, 2023). "It should be emphasized that, in some cancer types, GLS2 seems to play a tumor suppressor role." (PMID 38067269, 2023). "There is uncertainty as to whether GLS2 is predominantly a tumor suppressor or tumor promoter in some cases." (PMID 37627015, 2023). "Clearly, inhibition of GLS2 activity may reduce the survival of those cells in which GLS protein acts as a tumor promoter." (PMID 38067269, 2023). "Nevertheless, strong evidence suggests that GLS2 is a tumor suppressor in hepatic carcinoma." (PMID 37627015, 2023). "Notably, the GLS2 level in the tumor tissues of radioresistant patients was much higher than in those of radiosensitive patients." (PMID 38067269, 2023). "Notably, in this study, the GA core domain, located between positions 177 and 463, was necessary for the tumor-suppressive functions of GLS2 and its ability to promote ferroptosis." (PMID 38067269, 2023).